STX4 (syntaxin 4)
Diseases named in the same sentence as STX4 in open-access papers (continued):
Sharing a sentence is not in itself a finding about the gene and the disease.
cancer (8 papers, 2018 to 2024). A tumor composed of atypical neoplastic, often pleomorphic cells that invade other tissues. "Work from the cancer field identified STX4 serine 78 as a potential phosphorylation site that targets STX4 for proteasomal degradation; mutation of this serine to alanine resulted in a stabilized form of STX4." (PMID 33673206, 2021). "Syntaxin4 (STX4) gene encodes the protein STX4, a member of soluble N-ethylmaleimide-sensitive factor attachment protein receptors protein, playing a vital role in cell invadopodium formation and invasion, which is associated with the malignant progression of various human cancers." (PMID 34482824, 2021). "The TIMER database provided us with a visualization of the differential expression of STX4 in a range of cancers." (PMID 38226288, 2024). "Our study reveals that STX4 contributes to cancer progression by enhancing AKT expression and stimulating the activation of VEGF signaling pathways." (PMID 38226288, 2024). "This revealed that dysregulation of STX4 was connected with several known cancer-promoting pathways, including VEGF, NF−kappa B, and HIF−1 signaling pathways." (PMID 38226288, 2024). "STX4 expression was positively associated with CD8+ T-cell infiltration and negatively associated with M2-TAM infiltration in a majority of cancers." (PMID 38226288, 2024). "The “high” and “low” subgroups were always defined based on the mean expression value of STX4 in pan-cancer." (PMID 34482824, 2021). "In this study, we collected the mRNA expression of STX4 in 535 KIRC patients from The Cancer Genome Atlasthrough the University of California Santa Cruz Xena database platform." (PMID 34482824, 2021). "To further validate the results, we explored the expression of STX4 in pan-cancer data (32 other cancer types) from TCGA as an internal validation." (PMID 34482824, 2021). "As the pan-cancer analysis result shown that survival differences of STX4 existed in several types of cancer." (PMID 34482824, 2021). "Moreover, STX4 was found to be strongly associated with immune checkpoint genes across most tumors, and it correlated with TMB and MSI in several cancers." (PMID 38226288, 2024). "In vitro tests were conducted to examine the cancer-promoting role of STX4 in ccRCC." (PMID 38226288, 2024). "Research has shown that STX4 also plays an important role in several cancers." (PMID 34482824, 2021). "Additionally, although we validated the correlation between STX4 and immune checkpoint genes, TMB, and MSI by pan-cancer analysis, the specific mechanism still needs further investigation." (PMID 38226288, 2024). "Expression of SNAP23, Stx4 and other SNARES are often upregulated during the progression of cancers, indicating that LDL-cholesterol supports invasive potential via multiple Stx4/SNAP23-dependent trafficking events that are often de-regulated in cancer metastasis." (PMID 35806209, 2022).
tumor (8 papers, 2011 to 2024). "Despite these advances, a significant knowledge gap exists regarding the direct impact of STX4 on ccRCC cell proliferation and invasion and its potential influence on the tumor microenvironment." (PMID 38226288, 2024). "We evaluated the potential tumor-promoting function of STX4 in ccRCC cell lines through molecular studies." (PMID 38226288, 2024). "In this study, STX4 up-regulation was significantly associated with unfavorable clinicopathological features in KIRC, such as higher histological grade, larger tumor size, distant metastasis, and advanced AJCC stage." (PMID 34482824, 2021). "STX4 is one of the SNAREs proteins and is involved in cell invadopodium formation and tumor cell invasion." (PMID 34482824, 2021). "First, although differential STX4 expression was detected between tumor and normal real-world samples, the prognostic implication of this finding has not been demonstrated." (PMID 34482824, 2021). "These analyses demonstrated that the molecular functions of STX4 cover protein binding processes, protein transport processes, endosomal transport processes, and endocytosis, which suggest that STX4 influences the endo/exocytosis of the tumor." (PMID 34482824, 2021). "STX4 is involved in the formation of cell invadopodium and tumor cell infiltration." (PMID 38226288, 2024). "Additionally, in 786O and OSRC-2 cells, we conducted molecular experiments to gauge the potential tumor-promoting function of STX4." (PMID 38226288, 2024). "Nevertheless, whether STX4 impacts the proliferative and invasive abilities and tumor microenvironment of ccRCC remains to be investigated." (PMID 38226288, 2024). "Recent research has shown that STX4 mediates invadopodium formation and tumor cell invasion." (PMID 34482824, 2021). "The interaction between STX4 and Muncl18c facilitates invadopodium formation in tumor cells." (PMID 31474227, 2019). "Furthermore, the influence of STX4 on the ccRCC tumor microenvironment remains to be determined." (PMID 38226288, 2024). "Interestingly, we observed that STX4 was abnormally overexpressed during tumor progression." (PMID 38226288, 2024). "Cumulatively, these findings suggest that STX4 may function as a tumor enhancer in ccRCC." (PMID 38226288, 2024). "Thus, we speculated that STX4 may promote the tumor progression and influence the prognosis of KIRC by regulating endo/exocytosis, and autophagy." (PMID 34482824, 2021). "All results were consistent and suggested that STX4 may serve as a tumor promoter in KIRC." (PMID 34482824, 2021). "To validate STX4 mRNA expression in KIRC tissues, we performed qRT-PCR in 10 paired tumor and normal samples." (PMID 34482824, 2021). "Results had demonstrated that STX4 defines a domain for activity-dependent exocytosis in dendritic spines STX4 mediated trafficking of MT1-MMP during invadopodium formation and tumor cell invasion." (PMID 34482824, 2021). "In contrast, syntaxin 4-Δ29 expressing cells largely failed to form cysts but formed disorganized, tumor-like, solid structures lacking lumens and consisting of non-polarized cells." (PMID 21698262, 2011). "In addition, analysis using the TISIDB database to determine correlations with various chemokines showed that STX4 also had a positive correlation with CXCL9 and CXCL10, which contribute to a "hot" tumor microenvironment and can increase immunotherapy effectiveness." (PMID 38226288, 2024).
infection (5 papers, 2019 to 2025). The state of being infected such as from the introduction of a foreign agent such as serum, vaccine, antigenic substance or organism. "We found that the level of typhoid toxin in the infection media of STX4-deficient cells was significantly reduced in comparison to the parental cell line despite equivalent levels of toxin expression." (PMID 35579416, 2022). "STX4 and IFNγ had the most associated GO terms, highlighting the importance of these two genes in the overall immune response to pathogen infection, while SERPINE1 was associated with eight GO terms." (PMID 35510793, 2022). "The dysregulation of LD homeostasis caused by knocking down SNAP-23 and Syntaxin 4 revealed an important pathway during infection as it correlates with a defect in Chlamydia development." (PMID 32025513, 2019). "Instead, the loss of SNAP-23 and Syntaxin 4 results in a significant increase in Chlamydia-induced LDs, demonstrating that these SNAREs play an important role in controlling LD homeostasis during infection, which ultimately impacts Chlamydia development." (PMID 32025513, 2019). "Ten days post infection there was a near complete ablation of STX4 protein with a marked reduction of UCP1 protein concomitant with increased cleaved Caspase1." (PMID 38565851, 2024). "One possibility is that the increase in LD content observed in SNAP-23 and Syntaxin 4 KD cells during infection is due to a decrease in LD consumption by Chlamydia in these cells." (PMID 32025513, 2019). "Next, we investigated the impact of SNAP-23, Syntaxin 3, and Syntaxin 4 depletion on LD production during infection." (PMID 32025513, 2019). "To test the importance of SNAP-23, Syntaxin 3, and Syntaxin 4 during infection, we depleted HeLa cells of either of these SNAREs using the CRISPR/Cas9 system." (PMID 32025513, 2019). "Therefore, using CRISPR/Cas9 gene editing, we generated STX4- and STX11-deficient cells and examined the export of typhoid toxin in the resulting cells after infection with S. Typhi." (PMID 35579416, 2022). "Compared to the empty vector control cell line, we observed a ~71% and ~49% higher induction of LD content following infection in SNAP-23 and Syntaxin 4 KD cells, respectively." (PMID 32025513, 2019). "The addition of OA at the time of infection resulted in a substantial ~70% and ~67% increase in LD content compared to the empty vector control cell line in SNAP-23 and Syntaxin 4 KD cells, respectively." (PMID 32025513, 2019). "Since LD homeostasis is dysregulated during infection in SNAP-23 and Syntaxin 4 KD cells, we assessed the impact of increasing host cell FAs on Chlamydia-induced LDs in the SNAP-23 and Syntaxin 4 KD cell lines." (PMID 32025513, 2019). "We hypothesized that infection of HBMECs by NMEC can induce the expression of VAMP3 and syntaxin 4 via LPS." (PMID 40601634, 2025). "Consistent with their involvement in typhoid toxin transport, cells lacking SNAP23 or syntaxin 4 showed markedly reduced levels of typhoid toxin in the infection media." (PMID 35579416, 2022). "SERPINE1, STX4 and SEC31A, along with RAB35, are also involved in membrane trafficking and the innate immune response, which is an important initial host response to infection of cells with Chlamydia bacteria." (PMID 35510793, 2022). "Furthermore, since the induction of LDs by OA-treatment in non-infected cells was not affected by the absence of SNAP- 23 or Syntaxin 4, it is unlikely that the increase in LD content during infection is due to a global dysregulation in LD synthesis." (PMID 32025513, 2019).
neurological disease (2 papers, 2023 to 2025). "Interestingly, SETD1A and the STX1B distal target are both associated with neurological disorders, while the HSD3DB7 and STX4 distal targets are associated with immune-related and cardiometabolic diseases, respectively." (PMID 39727170, 2025).
STX4 also shares sentences with these, for which no sentence is quoted: metabolic disease (2 papers); ovarian carcinoma (2); psoriasis (2); schizophrenia (2); acute lymphoblastic leukemia (1); Alzheimer disease (1); ankylosing spondylitis (1); autism (1); breast tumor (1); diabetes mellitus type 1 (1); dilated cardiomyopathy (1); endocervical adenocarcinoma (1); epithelial carcinoma (1); glioma (1); head and neck cancer (1); Hypercholesterolemia (1); hypertrophic cardiomyopathy (1); insulinoma (1); Leigh syndrome (1); polycystic ovary syndrome (1); primary carnitine deficiency (1); sarcopenia (1); skin cutaneous melanoma (1); ulcerative colitis (1); uveal melanoma (1).